IL10 (interleukin 10)
Diseases named in the same sentence as IL10 in open-access papers (continued):
Sharing a sentence is not in itself a finding about the gene and the disease.
adenomyosis (11 papers, 2011 to 2025). The growth of endometrial tissue inside the muscular wall of the uterine corpus. "In patients with adenomyosis, the expression of several inflammatory cytokines, such as IL-1β, IL-6, IL-8, IL-10, TNF, NF-κB, MCP-1, and RANTES, is abnormal, and a variety of signaling pathways such as TLR437 and MAPK/ERK are involved." (PMID 36230643, 2022). "The cytokine IL10, which has potential anti-inflammatory effects, has been found to be reduced in expression in the endometrium of patients with adenomyosis." (PMID 35022045, 2022). "Our Immunohistochemistry results revealed that IL-10 expression was significantly lower in women with adenomyosis than in normal controls." (PMID 30687738, 2018). "To assess the mechanisms by which adenomyosis affects implantation, we detected the expression of the endometrial receptivity marker protein HOXA10 and the anti-inflammation cytokine IL-10 in women with adenomyosis." (PMID 30687738, 2018). "A previous study revealed a higher staining intensity for IL-10 in both the eutopic and ectopic endometrium of women with adenomyosis than in normal controls." (PMID 30687738, 2018). "The aim of this study was to investigate the potential role of IL-10 in regulating the receptivity marker HOXA10 in the endometrium of women with adenomyosis." (PMID 30687738, 2018). "IL-10 expression was reduced by 40% in the endometrium of women with adenomyosis compared with that in normal controls (P < 0.001)." (PMID 30687738, 2018). "Integrated optical density (IOD) measurements of the HOXA10 (P < 0.01) and IL-10 (P < 0.05) proteins were significantly lower in women with adenomyosis than in normal controls." (PMID 30687738, 2018). "Another study showed that IL-10 expression is lower in endometrium secretions from women with adenomyosis than in normal controls." (PMID 30687738, 2018). "The expression of p-STAT3 in the adenomyosis group was significantly lower than that in the control group, and there was a positive correlation between IL-10 and p-STAT3 protein levels in all the women examined." (PMID 30687738, 2018). "The expression levels of HOXA10 and IL-10 in the adenomyosis group were significantly lower than those in the control group, and there was a positive correlation between HOXA10 and IL-10 protein levels in all the women examined." (PMID 30687738, 2018). "In the context of adenomyosis, early IL-10 induction may represent a host attempt to counterbalance IL-6–driven inflammation and prevent excessive fibrosis." (PMID 41298316, 2025). "Elevated IL6 and altered IL10 dynamics have also been reported in human endometrial tissues from patients with adenomyosis, supporting the translational relevance of these cytokine patterns, which are known to influence endometrial receptivity and implantation success." (PMID 41298316, 2025). "For example, IL-6, IL-10, and IL-22 show altered expression in adenomyosis lesions." (PMID 39595579, 2024). "This may add to the interpretation of our previous findings that the expression of IL-10 and IL-10R is upregulated in the eutopic and ectopic endometrium of adenomyosis patients." (PMID 34289871, 2021). "Isolated total RNA from endometrial biopsy samples collected during the window of receptivity were used to verify whether selected candidate genes LIF, SOCS3, FOS, JUNB, IL6 and IL10 were differentially expressed between adenomyosis and control groups." (PMID 32933042, 2020). "We speculate that dysregulation of the IL-10/p-STAT3/HOXA10 signaling pathway results in embryo implantation failure in women with adenomyosis." (PMID 30687738, 2018). "However, IL-10 is significantly downregulated in adenomyosis, resulting in increased angiogenesis." (PMID 39595579, 2024). "An investigation of endometrial cytokine profiles indicated that IL-10 expression is lower in endometrium secretions from women with adenomyosis than in normal controls during the implantation window, which may correlate with compromised endometrium receptivity." (PMID 30687738, 2018).
adenomyosis (continued). "Hence, we propose that IL-10 may be a potential endometrial receptivity marker in patients with adenomyosis." (PMID 30687738, 2018). "Thus, the expression level of IL-10 in the endometrium of women with adenomyosis is unclear, and whether IL-10 is involved in the regulation of endometrial receptivity or embryo implantation needs to be further investigated." (PMID 30687738, 2018). "As IL-10 induced HOXA10 expression through phosphorylation of STAT3, we further detected p-STAT3 and STAT3 protein expression in the endometria of women with adenomyosis and normal controls." (PMID 30687738, 2018). "In this study, we aimed to characterize the molecular changes in IL-10 and HOXA10 in the endometrium in relation to subfertility in women with adenomyosis and to explore the potential regulatory relationship between these characteristics." (PMID 30687738, 2018). "Both IL-10 and HOXA10 levels in the endometrium are significantly reduced in women with adenomyosis compared with those in control women." (PMID 30687738, 2018). "The expression levels of IL-10, HOXA-10, STAT3, and p-STAT3 in the endometrium of women with adenomyosis and controls were examined by means of western blotting and immunohistochemistry." (PMID 30687738, 2018). "Another investigation found that the eutopic endometrium of women with adenomyosis exhibited a higher IL-10 staining intensity than that of normal controls." (PMID 30687738, 2018). "The abnormal expression of IL-10 and HOXA10 in the stroma might impair the decidualization of endometrial stromal cells in adenomyosis patients, which would result in implantation failure." (PMID 30687738, 2018). "Therefore, the exact functions of IL-10 and HOXA10 during decidualization in women with adenomyosis should be further assessed." (PMID 30687738, 2018). "However, the endometrial p(Y705)-STAT3 expression level was decreased by 50% in women with adenomyosis compared with that in normal controls (P<0.001), and the protein levels of p-STAT3 and IL-10 were positively correlated (r = 0.712, P < 0.01)." (PMID 30687738, 2018). "In this study, we demonstrated reduced IL-10, p-STAT3, and HOXA10 expression in the endometrium of adenomyosis patients, which might lead to impaired embryo implantation." (PMID 30687738, 2018). "For example, patients with adenomyosis have an increased number of macrophages, gamma delta T cells in ectopic and eutopic endometrium, and elevated preinflammatory factors and cytokines (e.g. TNF-α, IL-10, and IL-18) in the uterus and peritoneal fluid." (PMID 21385399, 2011). "Despite LIF, IL6, IL10, JUNB, FOS and SOCS3 showing no statistically altered expression patterns between study groups, their lower expression levels were observed in the adenomyosis group." (PMID 32933042, 2020).
airway allergy (11 papers, 2007 to 2025). "In contrast, sulfur compounds increased IFN-γ, IFN-β, IL-10, and IL-12 levels, enhancing innate immunity and thus playing a pivotal role in the expression of Th1 cytokines and treating allergic respiratory diseases in patients with a genetic predisposition." (PMID 36555240, 2022). "For example, defects in IL-10-producing T cells have been implicated in the immunopathogenesis of airway allergy, resulting in Th2-mediated production of allergen-specific IgE and tissue eosinophilia." (PMID 29616018, 2018). "In the murine model of airway allergy, IL-10-producing ILC2s produce high levels of IL-5 and IL-13 compared with non-IL-10 producers." (PMID 38788198, 2024). "The TIGIT+ ILC2s have low proliferative activity and low mRNA expression of Il5 and Il13, indicating that TIGIT+ IL-10+ exhausted-like ILC2s can be induced by severe acute and chronic airway allergy even in mice with intact Runx protein function." (PMID 38788198, 2024). "We found that, within the MLNC of chronically-infected mice, the CD19+ B-cell population exerts a suppressive effect on airway allergy, and that suppression is mediated in an IL-10-independent manner." (PMID 20306466, 2010). "In addition, it has been reported that the production of IL-10 by M2 macrophages suppresses airway allergy." (PMID 40635887, 2025).
Ascites (11 papers, 2016 to 2026). Accumulation of fluid in the peritoneal cavity (between the layers of the peritoneum that lines the abdomen). "The ROC curve analysis best predicted the risk of recurrence at an ascites IL-10 value of ≥369 pg/mL." (PMID 39199610, 2024). "We conclude that levels of IL-10 found in OC-associated ascites positively correlate with the inhibitory properties of ascites on the TLR-mediated up-regulation of the co-stimulatory molecule CD86, as well as the production of the cytokines IL-6 and IL-12p40 but not TNFα." (PMID 28410380, 2017). "To investigate whether the IL-10 dependent reduction in monocyte-derived DC activation in the presence of OC-associated ascites had an effect on APC functionality, we performed allogeneic MLR." (PMID 28410380, 2017). "While IL-10 levels in OC-associated ascites correlated with a reduced induction of most DC activation markers in our study, IL-10 levels did not correlate with the suppression of TNFα production indicating the presence of at least one other immunosuppressive factor." (PMID 28410380, 2017). "At the end of this study, we evaluated the predictive value of 12 cytokines for AP patients with ascites, and IL‐6, IL‐8, and IL‐10 still had good value." (PMID 38411379, 2024). "In dogs with SP, the concentrations of glucose, cfDNA, nucleosomes, PCT, CCL2, IL-6, IL-10, and KC-like were significantly different between blood and peritoneal effusion." (PMID 31316998, 2019). "We identify IL-10 and prostaglandin E2 (PGE2) as the pivotal immunosuppressive components in OC-associated ascites compromising TLR-mediated DC activation." (PMID 28410380, 2017). "Finally, a practical cut-off value for IL10 and a standardized and effective way of acquiring ascites are needed." (PMID 33911154, 2021). "Interestingly, IL-10 levels in OC-associated ascites did not significantly differ from levels in peritoneal fluid from patients with benign ovarian conditions." (PMID 28410380, 2017). "Notably, IL-10 levels surpass those found in non-malignant ascites and exceed the serum IL-10 levels within the same patient." (PMID 38279997, 2024). "Nevertheless, it is not evident whether IL10 is related to peritoneal tumor growth in patients without ascites." (PMID 33911154, 2021). "Unlike IL-10, PGE2 is absent from peritoneal fluid of patients with benign conditions and selectively reduces TNFα induction in response to TLR-mediated activation in the presence of OC-associated ascites." (PMID 28410380, 2017). "In order to confirm the presence of one or more additional immunosuppressive factors, we neutralized IL-10 in DC cultures activated with R848 in the presence and absence of ascites and compared the levels of CD86 up-regulation and cytokine induction between these two treatment conditions." (PMID 28410380, 2017). "However, in a study of several potential biomarkers in dogs, KC-like did not discriminate between septic peritonitis and nonseptic ascites, as did blood concentrations of CCL2 and peritoneal effusion concentrations of CCL2, IL-6, IL-10 and lactate." (PMID 39272157, 2024).
autoimmune uveitis (11 papers, 2012 to 2025). An autoimmune form of uveitis (disease). "IL-12p35 suppresses lymphocyte proliferation, induces expansion of IL-10-expressing and IL-35-expressing B cells and ameliorates autoimmune uveitis in mice by antagonizing pathogenic Th17 responses." (PMID 28959012, 2017). "The deletion of STAT3 in mouse B cells resulted in exacerbated experimental autoimmune uveitis, reduced murine IL-10+ and IL-35+ Breg frequency and reduced Treg expansion." (PMID 35660734, 2022). "The purpose of this study was to evaluate the therapeutic efficacy of a single intravitreal (IVT) dose of AAV8-Equine-IL10 gene therapy for inhibition of experimental autoimmune uveitis (EAU) in rats." (PMID 35980983, 2022). "Moreover, autoimmune uveitis in patients may be associated with polymorphisms of TNF and IL10 genes." (PMID 39684616, 2024).
cardiac arrest (11 papers, 2009 to 2021). Cessation of breathing and/or cardiac function. "Inflammatory cytokines, such as IL-6, IL-10, and TNF-α, have been associated with cardiovascular dysfunction in patients with cardiac arrest." (PMID 33510459, 2021). "From our data we conclude that mild hypothermia initiated after successful resuscitation from cardiac arrest reduces pro-inflammatory cytokine, IL-10, and ICAM-1 mRNA expression compared to normothermia." (PMID 20158893, 2010). "This syndrome is associated with both complement activation and an intense increase of various inflammatory mediators (IL-1, IL-6, IL-8, and IL-10) as early as 3 hours after cardiac arrest, and thus affords potential targets for new treatments." (PMID 20150958, 2009). "Epoxide hydrolases are also involved in the regulation of neuroinflammation and inhibition of soluble epoxide hydrolases resulted in decreased pro-inflammatory cytokines (IL-1β and Il-6) within the context of seizures, and increased IL-10 secretion in the CNS following cardiac arrest." (PMID 29040522, 2018). "Whereas the proinflammatory immune reaction started immediately after cardiac arrest in our study, anti-inflammatory cytokine dynamics started minimally temporally delayed demonstrating significant higher IL-10 mRNA levels 48 h and 72 h after the beginning of CPR in nonsurvivors." (PMID 29445259, 2017). "Cardiac arrest and ECPR markedly increased the plasma levels of IL-10, VEGF, leptin, TNF-α, IL-1β, IL-6, fractalkine, IL-5, IL-18, IP-10, IL-4, eotaxin, MIP-1α, IL-17α, IL-12, RANTES, G-CSF, LIX, and MCP-1." (PMID 34781966, 2021).
eczema (11 papers, 2014 to 2026). "The T:T genotype shows greater IL‐7R mRNA expression, but in the context of dog exposure, the risk effect is overshadowed by an increase in cytokines and chemokines in the IL‐10 pathway that suppress eczema to a greater extent in T:T than C:C individuals." (PMID 40462597, 2025). "Clinical studies suggest that the mechanism of MTMZM in treating eczema may be related to regulating the expression of IL-2, IL-4, IL-10, and γ-IFN; therefore, it can improve the body's immunity and reduce inflammatory response." (PMID 40933470, 2025).
enteropathy (11 papers, 2012 to 2025). "However, there is accumulating evidence for early alloHSCT being the only curative therapeutic approach for patients suffering from monogenic PIDs causing severe enteropathy, such as IL10/IL10R deficiency, the IPEX syndrome, and CTLA-4 deficiency." (PMID 28197149, 2017). "The administration of B. longum CECT 7347 to the enteropathy model significantly reduced TNFα (P = 0.003) and increased IL-10 (P<0.001) production, indicating its ability to counteract the inflammatory response in the intestinal mucosa." (PMID 22348021, 2012). "In addition, our results evidence significant differences between the immunomodulatory properties of B. longum CECT 7347 and L. casei ATCC 9595, since this latter strain was unable to rescue IL-10 production in the enteropathy model of HLA-DQ8 transgenic mice." (PMID 22348021, 2012). "Finally, IL-10, an anti-inflammatory mediator secreted by Tregs and capable of modulating both intestinal damage in T-cell mediates enteropathy, and Th17 pathogenicity, was significantly augmented in serum samples after one week of discontinuing tacrolimus treatment." (PMID 39854413, 2025). "B. longum CECT 7347 administration increased NFκB expression and IL-10, but reduced TNF-α, production in the enteropathy model." (PMID 22348021, 2012). "Furthermore, in the gliadin-induced enteropathy animal model, this strain has been shown to reduce the peripheral CD4+ T cells, rise IL-10, and shrink TNF-α production." (PMID 31013929, 2019).
esophageal squamous cell carcinoma (11 papers, 2016 to 2025). Esophageal squamous cell carcinoma (ESCC) is a type of esophageal carcinoma (EC) that can affect any part of the esophagus, but is usually located in the upper or middle third. "In another study, the expressions of CD8+, CD4+, FOXP3+, Immunoglobulin G4 (IgG4), and IL-10 and clinical information of 118 patients with esophageal squamous cell carcinoma (ESCC) were assessed with hematoxylin and eosin (H&E), immunohistochemistry (IHC) staining and multi-color Immunofluorescence." (PMID 38077386, 2023). "In addition, the IL-10 rs1800896 gene polymorphism increased the risk of laryngeal SCC (AG/AA: OR = 1.41, 95% CI: 1.04–1.93, p = 0.030), esophageal SCC (AG + GG/AA: OR = 0.48, 95% CI: 0.32–0.72, p = 0.000)." (PMID 37077342, 2023). "The present study recruited 721 esophageal squamous cell carcinoma (ESCC) cases and 1208 controls and explored the roles of single nucleotide polymorphisms (SNPs) in the interleukin-4 (IL-4), IL-10, and herpesvirus entry mediator (HVEM) genes in contributing to ESCC risk." (PMID 32744314, 2020). "We investigated the density, distribution and relationship of five immune markers CD4, CD8, Foxp3, IL-10 and IgG4 with multiple immunostaining method in 118 esophageal squamous cell carcinoma (ESCC) together with clinical data." (PMID 36891293, 2023). "In esophageal squamous cell carcinoma (ESCC), differentially methylated CpG sites between cancer tissue and healthy tissue were found in genes in the IL10 signaling pathway; IL-6 was found to be hypomethylated, while IL-1α was found to be hypermethylated." (PMID 34901003, 2021).
hemorrhage (11 papers, 2009 to 2025). Loss of blood from the vascular compartment to the exterior or into nonvascular body space as a result of rupture or severance of the blood vessels. "By multi-variate logistic regression, we finally included the EASIX score and IL-10 as statistically significant predictors to set a risk-stratification model for hemorrhage after CAR T-cell therapy." (PMID 37814134, 2023). "In fact, an inverse relationship between the quantity of iron accumulated in the CCM and IL-10 was reported after a symptomatic hemorrhage." (PMID 35109870, 2022). "Patients with haemorrhage-hepatitis syndrome had lower concentrations of IFN-α, IFN-λ2/3, IL-1β and IFN-γ and higher levels of IP-10, IFN-λ1, IL-6, IL-10, TNF-α and GM-CSF." (PMID 37090924, 2023). "Relative to levels of the pre-hemorrhage (0 min), the plasma levels of IL-4 were not significantly increased, while IL-10 was significantly increased at 90 and 180 min (by about 1.5 and twofold) post-REBOA in the 25 min REBOA + TRIC37°C group." (PMID 34211011, 2021). "In contrast, we only observed a nonsignificant increase of splenic IL-10 release following femoral fracture and hemorrhage in WT animals." (PMID 22496597, 2012). "In contrast to WT animals, splenic IL-10 release was significantly decreased following femoral fracture with and without hemorrhagic shock." (PMID 22496597, 2012). "A statistically significant difference in circulating IL-10 was observed between survivors and non-survivors at 15 min post-surgical baseline as well as at 15 and 60 min post-hemorrhage." (PMID 20027315, 2009).